RPL7L1 (ribosomal protein L7 like 1)
Synonyms: dJ475N16.4
Tractability: Small molecule: a structure with a bound ligand is known. PROTAC: ubiquitination databases record sites on it; its protein half-life has been measured.
Gene: Protein-coding gene on chromosome 6 (42,879,616 to 42,889,925, forward strand). Ensembl gene ENSG00000146223.
Subcellular location (Human Protein Atlas): Mitochondria; Nucleoli
Gene Ontology:
Molecular function: protein binding; RNA binding
Biological process: maturation of LSU-rRNA from tricistronic rRNA transcript (SSU-rRNA, 5.8S rRNA, LSU-rRNA)
Cellular component: mitochondrion; cytosolic large ribosomal subunit; nucleolus
Genetic constraint (gnomAD): Loss-of-function variants: 9 observed, 14.63 expected, observed/expected ratio (o/e) 0.62, 90% interval 0.37 to 1.07. The upper end of that interval is the gene's LOEUF score, 1.07, which puts it in group 4 of 6, group 1 being the genes least tolerant of losing a copy. Missense variants: 143 observed, 166.62 expected, observed/expected ratio (o/e) 0.86, 90% interval 0.75 to 0.99. Synonymous variants: 67 observed, 58.92 expected, observed/expected ratio (o/e) 1.14, 90% interval 0.93 to 1.39.
Homologues: Orthologues: chimpanzee RPL7L1 (99% identical), macaque RPL7L1 (95% identical), dog RPL7L1 (87% identical), pig RPL7L1 (86% identical), rat Rpl7l1 (85% identical), mouse Rpl7l1 (81% identical), guinea pig RPL7L1 (78% identical), zebrafish rpl7l1 (59% identical), tropical clawed frog rpl7l1 (55% identical), Caenorhabditis elegans rpl-7 (38% identical), Drosophila melanogaster RpL7 (36% identical). Paralogues in human: RPL7 (42% identical).
Diseases named in the same sentence as RPL7L1 in open-access papers:
RPL7L1 is named in the same sentence as 3 diseases in open-access papers, as found by Europe PMC text mining. Sharing a sentence is not in itself a finding about the gene and the disease. The quoted sentences say what the papers report.
Obesity (1 paper, 2024). Accumulation of substantial excess body fat. "Our results observed that low mRNA expression of RPL7L1 contributed to obesity in pigs, providing a novel insight into its role in fat deposition, and this needs to be further explored and confirmed." (PMID 38832038, 2024).
infection (1 paper, 2023). The state of being infected such as from the introduction of a foreign agent such as serum, vaccine, antigenic substance or organism. "Proteins downregulated during later stages of MVA infection showed a strong tendency to self-associate, including nuclear pore components, and a selection of nucleolar proteins associated with ribosome biogenesis (e.g. SURF6, RBM28, RPL7L1, ZC3HAV1, CDK105)." (PMID 38065956, 2023).
tumor (1 paper, 2024). "We pinpointed 8 human-derived genes (PHF14, PELP1, RPL7L1, HPRT1, RELN, RNU1-75P, RNU5A-8P, RNVU1-19), likely to represent tumor-specific signals as a signature combining these genes demonstrated high accuracy in assessing therapy response." (PMID 39337470, 2024).